ATG7 (autophagy related 7)
Diseases named in the same sentence as ATG7 in open-access papers (continued):
Sharing a sentence is not in itself a finding about the gene and the disease.
cancer (continued). "Similarly, mouse strains lacking the essential autophagic genes ATG5 and ATG7 develop liver damage, inflammation and benign liver tumors unable to progress to carcinoma." (PMID 30067838, 2018). "Besides, cancer cells lacking Atg7 gene are insensitive to response to the compounds-induced autophagy." (PMID 28404910, 2017). "Meanwhile, cancer cells lacking Atg7 gene are insensitive to small-molecules-induced autophagy." (PMID 26811496, 2016). "In addition, the expression levels of autophagy markers such as Beclin-1, ATG5, ATG7, and LC3II conversion were significantly higher in human tumors compared to adjacent nontumor tissues, demonstrating the correlation with upregulation of autophagy function in cancer cells." (PMID 33806593, 2021). "Moreover, it was found that though ATG7 depletion alone could not reduce cancer cell viability, this depletion led to heightened sensitivity to the knockdown of BRAF and CRAF." (PMID 34830283, 2021). "Collectively, these data showed that ATG7 was involved in TIME in HNSCC, and it potentially did not function in cancer cells." (PMID 36262348, 2022). "Studies have shown that under nutrient-sufficient conditions, the proliferation of some KRAS-mutant cancer cell lines is not strongly affected, or is relatively little affected, by pharmacological inhibition of autophagy, RNAi-mediated acute ATG5/ATG7 knockdown, or CRISPR-mediated ATG7 knockdown." (PMID 39272847, 2024).
infection (71 papers, 2009 to 2025). The state of being infected such as from the introduction of a foreign agent such as serum, vaccine, antigenic substance or organism. "Atg7-deficient mice exhibit higher proportions of neutrophils and phagocytic cells in the early phase of infection." (PMID 39971913, 2025). "The percentage of dead cells in ATG7 KO iPSDM was significantly higher after infection with Mtb WT, indicating that, in ATG7 KO cells, the infection was associated with macrophage cell death." (PMID 36959508, 2023). "For example, atg7 deficiency led to impaired host defense in macrophages, and thus resulting in magnified infection, inflammation, and worsened injuries in the lung of animals infected by K. pneumoniae." (PMID 34211859, 2021). "A recent report showed that Pa infection enhanced autophagy, and that Atg7-/- mice showed enhanced susceptibility to infection and impaired bacterial clearance." (PMID 26735693, 2016). "Infection with shAtg7 encoding lentivirus reduced the Atg7 protein levels as shown Western blot compared to the negative control virus." (PMID 25787015, 2015). "Knockdown of Atg7 was associated with moderate reductions in CXCL8 production induced by RV16 infection or poly(I:C)." (PMID 25541728, 2014). "However, the mechanistic details regulating such time lapse change in immune cells population during pathogen infection in ATG7 deficient mice remain to be explored yet." (PMID 39971913, 2025). "ATG7 has also been linked to pathogen infections but its role is highly context-dependent." (PMID 38227600, 2024). "Quantitative PCR (qPCR) analysis revealed a significant upregulation of ATG7 mRNA expression at 36 and 48 h post infection." (PMID 40176193, 2025). "Inhibition of autophagy after infection resulted in increased p62 levels and decreased Beclin-1, ATG7, and ATG5 levels, similar to the response to IFITM3 knockdown, whereas overexpression of IFITM3 had the opposite effect." (PMID 40681213, 2025). "With ATG5 and ATG7 KO cell lines, cells have to adapt to survive during the amplification procedure following infection." (PMID 39851574, 2025). "Although it is well known that autophagy plays crucial roles in the infections with various viruses including influenza A virus (IAV), function and underlying mechanism of ATG7 in infection and pathogenesis of IAV remain poorly understood." (PMID 38227600, 2024). "Then, we generated A549 cells expressing either wild type (WT) ATG7, each ATG7 mutant, or EV control, followed by infection with IAV." (PMID 38227600, 2024). "The Lc3b, Beclin1, Atg7, and Atg12 mRNA levels were significantly lower at four and six weeks after infection than those in the uninfected group." (PMID 38393131, 2024). "Infection with lentivirus, bearing Atg-7, later enabled Atg7 to return to normal levels and reactivate autophagy, restoring Aβ secretion to its prior levels." (PMID 37962467, 2024). "The mRNA expression levels of Atg7 were 0.68 ± 0.12, 0.46 ± 0.12, and 0.32 ± 0.099, respectively, which were significantly lower than those before infection (1.0 ± 0.16) (F = 33.79, p < 0.01)." (PMID 38393131, 2024). "This study showed that liver autophagy-related Beclin1, p62, LC3BII/I, Atg7, and Atg12 levels decreased significantly at two, four, and six weeks post-infection." (PMID 38393131, 2024). "ATG7 can limit the infection of mycobacterium tuberculosis, human papillomavirus, Chikungunya virus, and poliovirus." (PMID 38227600, 2024). "We generated A549 cells expressing either WT ATG7, each ATG7 mutant, or EV control, followed by infection with IAV." (PMID 38227600, 2024). "Conversely, excision of other core autophagy genes including Atg5, Atg7, Atg14, and Atg16l1 from the mice macrophages showed moderate to severe level vulnerability to pathogen infection and bacterial burden." (PMID 37180758, 2023). "In the case of induced whole-body atg7 deletion in adult mice, most mutant mice die within 2–3 months due to infection and neurodegeneration." (PMID 36871041, 2023).
infection (continued). "Mtb signal per macrophage increased approximately three-fold in ATG7 KO iPSDM versus two-fold when compared with WT iPSDM after 96 h of infection." (PMID 36959508, 2023). "The increase in bacterial replication was observed only during infection with Mtb WT since both the Mtb ΔesxBA and ΔcpsA mutants were restricted in the ATG7 KO iPSDM." (PMID 36959508, 2023). "Our data show that ATG7- and ATG14-dependent restriction and induction of cell death is primarily associated with Mtb WT infection." (PMID 36959508, 2023). "In the fly brain, NF-κB induces the expression of Atg5 and Atg7, and thus triggers autophagy activation against infection with Zika virus." (PMID 35159248, 2022). "Zika virus (ZIKV) triggers NF-κB-dependent inflammatory signaling in the fly brain and induces the expression of Atg5 and Atg7, leading to autophagy activation in neurons and limiting the infection and proliferation of ZIKV in this organ." (PMID 35159248, 2022). "ATG5 and ATG7 transcript levels were only slightly increased at 24 h post-infection, and this increase was essentially detected at 48 h post-infection." (PMID 36298785, 2022). "ATG7‐dependent autophagy is also stimulated upon infection with Influenza A, leading to endogenous presentation of epitope on MHC class II molecules." (PMID 34725936, 2021). "Here we demonstrated that the integrity of intestinal-epithelium barrier and function are damaged with a greater extent in Atg7-/-;Stk11-/- mice compared with Stk11-/- mice, leaving the mice vulnerable to infection." (PMID 33236987, 2020). "Treatment with autophagy inhibitors or silencing of ATG5, ATG7, and ATG8h promoted TLCYnV infection in solanaceous plants." (PMID 32373106, 2020). "First, monitoring of autophagic flux following infection revealed a marked reduction of Atg7 and LC3B expression profile and low accumulation levels of autophagy-related LC3-I, LC3-II, and the Atg12–Atg5 protein complex." (PMID 32064256, 2019). "Upon infection, the expression of autophagy-related genes Atg7 and LC3B at the RNA level was significantly restored in treated cells when compared with untreated cells." (PMID 32064256, 2019). "We observed that expression of ATG7, a mediator of autophagy, is upregulated upon infection with unopsonized B. thailandensis, suggesting that uptake of unopsonized pathogen can lead to phagosomal escape that triggers autophagy." (PMID 28638804, 2017). "In wild-type MEF cells, ~25% more L. dumoffii remained viable in comparison with in Atg7 knockout MEF cells at five hours post infection." (PMID 28317932, 2017). "We also demonstrate that Lyn’s activity is required for inhibiting Pa infection, as depletion of Lyn and/or Atg7 in macrophages resulted in increased Pa growth." (PMID 26735693, 2016). "Reduction or depletion of Atg7 showed decreased cell viability and reduced bactericidal activity upon Pa infection." (PMID 26735693, 2016). "Knockdown of miR-20a, through infection of anti-miR-20a-LV, in SiHa cells increased ATG7 and TIMP2 protein levels." (PMID 25803820, 2015). "The specificity of genetic knockdowns of mTOR, Beclin-1 and Atg7 have confirmed that HPV-induced restraint of autophagy is important for early infection events." (PMID 25202355, 2014). "Our results implied that promoter activity was enhanced as the infection proceeded, and disruption of Atg5 and Atg7 function further accelerated the activity." (PMID 23320079, 2013). "Infection of C. parvum leads to up-regulation of Beclin-1, ATG7, and ATG5." (PMID 40681213, 2025). "Furthermore, we generated ATG7 knockdown A549 cells re-expressing either WT or mutants of ATG7, followed by infection with IAV." (PMID 38227600, 2024). "In addition, ATG7-dependent autophagy is stimulated upon infection with IAV, leading to the formation of memory CD8+ T cell and endogenous presentation of epitope on MHC class II molecules." (PMID 38227600, 2024).
infection (continued). "Therefore, we further detected the expression levels of Beclin1, Atg5, and Atg7 at 8 h after infection, and found that the levels of these three autophagy-related proteins in BCG-infected macrophages were higher than those in the blank group (p < 0.05)." (PMID 37256106, 2023). "Here, we tentatively speculate that ATG7 played an important role in antagonistic PAstV infection according to the crosstalk between autophagy and apoptosis, which needs to be further verified." (PMID 35891364, 2022). "Thus, ATG5 and ATG7 core autophagy factors were involved in the augmented lipidation of LC3 observed during the DUGV infection of Huh7 cells." (PMID 36298785, 2022). "Similarly, both ATG7 mRNA and protein levels were significantly upregulated 48 hours after infection with ad-ATG7, as well as LC3-II protein, with respect to ad-LacZ control." (PMID 35365624, 2022). "In addition, ATG7 deficiency attenuated virus-induced degradation of MAVS, and reconstitution of ATG7 in ATG7-/- cells restored the degradation of MAVS following SZ19-ΔF2 infection." (PMID 33577621, 2021). "Notably, the expression of Atg7 was significantly increased by E16 infection at the LG condition (1.48 ± 0.08-fold, p = 0.02) and in cells grown in NT (1.26 ± 0.2-fold, p = 0.001) compared with uninfected cells." (PMID 32676816, 2020). "We next generated ULK1, BECN1, and ATG7 THP-1 cell lines to test whether HIV-1 CA P90A infection could similarly induce the expression of pro-inflammatory genes in cells lacking autophagy." (PMID 33052966, 2020). "As expected, ATG5, Beclin-1, ATG7 and ATG16L1 deficiency led to impaired conversion of endogenous LC3-I to LC3-II and decreased number of LC3 puncta following SH0165 infection." (PMID 31106159, 2019). "We used lentiviral infection to inhibit expression of ATG7 in immunopurified CD34+ CML cells." (PMID 29228587, 2017). "To determine whether the opsonization state of Burkholderia can affect stimulation of macroautophagy, we quantified expression of ATG7, a regulator of autophagosome formation, in response to infection with unopsonized and serum-opsonized Bt CDC2721121." (PMID 28638804, 2017). "However, our findings, along with other reports, demonstrate that mutations or absence of Atg7, Atg4b, LC3b, or Atg16L1 can trigger a protective response against the infection." (PMID 39971913, 2025). "In a murine Pseudomonas aeruginosa infection, NO enhanced bacterial clearance via an Atg7-mediated mechanism that also reduced IFN-γ activity,inhibited ROS production, and limited oxidative stress, resulting in decreased lung injury and lower infection-associated mortality." (PMID 36917159, 2023). "We first examined whether SIRT-1 colocalizes with ATG-7 during EV-D68 infection." (PMID 37850626, 2023). "However, the role of ATG7 in human models of infection remains context‐specific." (PMID 34725936, 2021). "Interestingly, we found that nuclear fragmentations typical for apoptosis following MV-Edm infection occurred exclussively in autophagy knockdown cells treated with ATG7, BECN1 and SQSTM1 siRNA, respectively, whereas nuclei within syncytia remained intact in control siRNA treated cells." (PMID 25004098, 2014). "IFITM3 overexpression up-regulated LC3B II/LC3B I, Beclin-1, ATG7, and ATG5, but down-regulated p62 during infection." (PMID 40681213, 2025). "In this study, infection by C. parvum up-regulated the ratio of LC3B II to LC3B I, p62, Beclin-1, ATG7, and ATG5." (PMID 40681213, 2025). "As expected, ATG7 overexpression markedly increased IAV titers and elevated viral NP mRNA levels in A549 cells compared to control, in response to infection with H1N1 IAVs including WSN and PR8." (PMID 38227600, 2024).
infection (continued). "At four and six weeks following infection, the levels of Beclin1, LC3BII/I, Atg7, and p62 proteins were considerably lower than those in the uninfected group." (PMID 38393131, 2024). "The expression of ATG5, ATG7, ATG12, and LC3 in BMDMs was remarkably enhanced after both BCG and H37Rv infection." (PMID 38016969, 2023). "Similar to the ATG7 KO iPSDM infected with Mtb WT, most of the ATG14 KO iPSDM underwent cell death after Mtb WT infection, precluding fixed cell image-based analysis." (PMID 36959508, 2023). "ATG7, or ATG7 combined with ATG5 for an optimal effect, were thus targeted for silencing for 48 h prior to infection at two MOI (0.1 and 0.001)." (PMID 36298785, 2022). "Infection with vaccinia, the live virus used in the smallpox vaccine, induces LC3 lipidation independently of ATG7 and ATG5." (PMID 34725936, 2021). "A time-course coculture experiment was performed with Mock-, ATG5- and ATG7-KO Hep3B cells infected with H. hepaticus and its CDT corresponding ΔCDT strain and the effects of the infection following gene extinction were analyzed." (PMID 33662035, 2021). "H37Ra infection leads to downregulation of miR-106a in a time- and dose-dependent manner and concomitant upregulation of its three targets (ULK1, ATG7, and ATG16L1) in THP-1 macrophages." (PMID 33505399, 2020). "For instance, Beclin1, PI3K/VPS30, and ATG3 are all required to limit HR PCD to the pathogen infection site, ATG5 and ATG7 regulate glucose-induced ROS in Arabidopsis, and ATG9 is a negative regulator of innate immune signaling." (PMID 32373106, 2020). "The truncated LC3/GABARAP proteins cannot be further processed by ATG7 and ATG3, thereby irreversibly inactivating them during infection." (PMID 31450711, 2019). "We found that both MARCKS and ATG7 transcript levels were reduced ~2- and ~5-fold, respectively, in cells depleted of PKC-η, compared to control siRNA-treated cells (CTL) upon infection with unopsonized Bt CDC2721121." (PMID 28638804, 2017). "This notion is supported by evidence showing that intracellular infection with Francisella down-regulates several autophagy-related genes in THP-1 human monocytes, including ATG5, ATG12, ATG16L2, ATG7, ATG4A and class III PI3K." (PMID 20003180, 2009). "At the initial phase of infection, an increase in neutrophils along with monocytes and macrophages with no change in dendritic cells has been observed in the absence of ATG7." (PMID 39971913, 2025). "We found that all the mice inoculated with TRAP/FlpL or Atg7 cKO/WT sporozoites became patent on day 3 postinfection (p.i.), whereas parasites lacking Atg7 (Atg7 cKO) failed to initiate blood-stage infection." (PMID 39714137, 2025). "Since mouse is an ideal animal model for infection with PRV, a DNA virus, we also determined whether ATG7 was involved in the pathogenesis of PRV." (PMID 38227600, 2024). "As expected, after infection of ATG7 KO iPSDM with Mtb WT, ΔesxBA or ΔcpsA, there was no induction of LC3B processing." (PMID 36959508, 2023). "Moreover, conditional ablation of Atg5 or Atg7 in peripheral blood-derived CD8+ T cells (also known as cytotoxic T lymphocytes) induces defective autophagy flux, pathogen infection, and survival defects in memory T cells." (PMID 37180758, 2023). "After infection of MDM, there were higher replication rates with both Mtb WT (2.6-fold) and ΔesxBA (0.3-fold) in MDM lacking ATG14 than in WT or ATG7-deficient MDM." (PMID 36959508, 2023). "There were no marked changes noted in the expression of Becn1, Atg5, Atg7, Atg12, Atg16l1 or Atg16l2 both before and 6 h after infection." (PMID 35903351, 2022). "ATG7‐mediated LC3 lipidation is also required for the exocytic release of cathepsin K by osteoblasts, and LC3‐positive lysozyme‐containing granules are released by Paneth cells upon infection." (PMID 34725936, 2021). "Therefore, the relative expression of autophagy-related genes, Atg7 and LC3B, were gradually decreased in a time-dependent manner following infection." (PMID 32064256, 2019).